GLO1 (glyoxalase I)
Diseases named in the same sentence as GLO1 in open-access papers (continued):
Sharing a sentence is not in itself a finding about the gene and the disease.
tumor (continued). "Further associations between MG metabolism and the spliceosome were the positive correlation of Glo1 expression with expression of spliceosomal genes in human tumor cell lines and clinical human tumors and MG modification detected on 16 spliceosome pathway proteins." (PMID 34790575, 2021). "Literature suggests that, in case of ATC, the implementation of MG scavengers (e.g., aminoguanidine) and Glo1 activators (e.g., resveratrol) decreases MG level, activates Glo1 and, as a consequence, eases off tumor aggression due to changes in processes of its invasion and migration." (PMID 34575195, 2021). "In addition, multidrug resistance to the chemotherapeutic agents in tumor cells was promoted through Nrf2 signaling during high glycolytic activity and Glo1 expression." (PMID 33466626, 2021). "Spliceosomal gene expression correlated positively with Glo1 in human tumor cell lines and tumors." (PMID 34790575, 2021). "Second, we wanted to investigate whether Glo1/MG pathway might be involved in the refractoriness of this neoplasia to PD-L1/PD-1-based immunotherapy, with a particular interest on the PD-L1-directed monoclonal antibody, atezolizumab." (PMID 34199263, 2021). "Glo1 regulates tumor cell survival and proliferation through different mechanisms." (PMID 33396745, 2020). "Upon necropsy, lungs from animals injected with A375-GLO1_WT displayed pronounced metastatic pathology, largely absent from tissue obtained from A375-GLO1_KO-injected mice, and tumor multiplicity was attenuated as a result of GLO1 genetic deletion [3 ± 1 versus 18 ± 4 (tumors per lung; p < 0.001);]." (PMID 32466621, 2020). "Moreover, a role of the tumor suppressor miR-101 in the control of GLO1 expression as a determinant of methylglyoxal-induced posttranslational modification of specific protein targets (including HSP40) was substantiated." (PMID 32466621, 2020). "Tumors from Glo1-deleted cells also had increased MG-H1 protein adducts, suggesting that accumulation of methylglyoxal-derived adducts might contribute to reduced tumor growth." (PMID 31811141, 2019). "This could suggest that Glo1 is upregulated during tumor progression or that there is positive selection for increased capacity for methylglyoxal detoxification in tumors." (PMID 31811141, 2019). "Hence, the traditional role of Glo1 as a tumor promoting factor appears to complement an emerging, novel role of this metabolic enzyme as a tumor suppressor." (PMID 31174324, 2019). "The potential complication of cytotoxic off-target effects in the surrounding non-tumor brain tissue (neurons, astrocytes, and oligodendrocytes) resulting from GLO1 inhibition was investigated using quantitative immunohistochemistry to assess markers of apoptosis and neural fitness." (PMID 29385725, 2018). "One possibility is that patients could be selected for GLO1 inhibition treatment based on MRS tumor profiling and then be monitored for treatment response by pharmacodynamic CEdG metabolite biomarkers quantified by the sensitive LC-ESI-MS/MS method used here." (PMID 29385725, 2018). "However, with the exception of one sample, they found Glo1 and Glo2 activity essentially identical between tumor and non-tumor samples." (PMID 29385039, 2018). "Residual primary and metastatic tumours with the growth advantage of Glo1 overexpression may impact negatively and markedly so on survival." (PMID 29100361, 2017). "The presence of nuclear GLO1 might serve as a potent defense mechanism to protect key regulators of DNA repair and tumor cell survival in the nucleus from inactivation by MG-induced modification." (PMID 28549423, 2017). "However, for cases showing increased Glo1 Digital-IHC Score in tumour versus non-tumour tissue, there was a positive correlation of change in Glo1 Digital-IHC Score with Glo1 copy number: r = 0.62, P = 0.025; Pearson (n = 13)." (PMID 29100361, 2017). "In a survey of 520 human tumours, increased GLO1 copy-number was found at a mean prevalence of 8%." (PMID 29100361, 2017).
tumor (continued). "GLO1 depleted cells showed an increase in tumor growth compared to control cells." (PMID 28117708, 2017). "We could access further archived sample tissue for immunohistochemistry (IHC) analysis of Glo1 protein in tumour and non-tumour tissue in 29 cases; 7 pNET and 22 midgut NET." (PMID 29100361, 2017). "However, others and we recently established that GLO1 must also be considered as a tumor suppressor." (PMID 28117708, 2017). "Analysis of GLO1 copy-number variation particularly in patients with midgut NET could be a novel prognostic marker for tumour progression." (PMID 29100361, 2017). "Additionally, AGE, AdipoR1 and Adipo R2 expression was related to tumor grade, whereas GLO-1 and AdipoR1 to T-category." (PMID 26931562, 2016). "In addition, a positive correlation between the amount of GLO1 protein and tumor grade has been described in breast tumor biopsies." (PMID 27999356, 2016). "A difficulty in clinical translation is identifying tumours that are sensitive to Glo-1 inhibitors." (PMID 27406712, 2016). "In support of this concept, previous studies reported that a specific Glo-1 inhibitor, S-p-bromobenzyl-glutathione cyclopentyl diester (SpBrGSHCp2), demonstrates an anti-tumor effect against Glo-1-overexpressing tumors that are unresponsive to conventional therapies." (PMID 24978626, 2014). "However, tumour cells with high glyoxalase I expression have higher levels of DNA glycation adducts than those with relatively lower expression suggesting that glyoxalase I expression increases to try to counteract methylglyoxal-induced cytotoxicity." (PMID 22778743, 2012). "Moreover, qRT–PCR and IHC experiments disclosed a correlation of increased GLO1 expression with local tumor progression and lymph node invasion." (PMID 22479608, 2012). "In addition, overexpression of glyoxalase I and glyoxalase II has been correlated with multidrug resistance in tumours." (PMID 22778743, 2012). "In tumor tissues high activities of glyoxalase I have also been reported." (PMID 19710909, 2009). "Moreover, non-pharmacological interventions, like peritumoral electroacupuncture, have also been demonstrated to increase tumor sensitivity to chemotherapeutic agents by inhibiting GLO1, further strengthening the potential of GLO1 as a targeted therapeutic indicator." (PMID 40352588, 2025). "Moreover, MG derivative MG-H1 down-regulates PD-L1 expression in tumor cells in metastatic prostate cancer (mPCa), whereas high expression of GLO1 limits the accumulation of MG-H1 and maintains the expression of PD-L1, which inhibits CD8+ T cell function and promotes immune escape in mPCa." (PMID 40352588, 2025). "Therefore, protection of spliceosome pathway proteins may confer another role of GLO1 in tumour cells." (PMID 35409048, 2022). "Tumor hypoxia may activate KDM4A demethylation to drive increased GLO1 copy number." (PMID 35269594, 2022). "Taking into account all this, we examined whether the decreased PD-L1 expression, determined by MG-H1 accumulation through Glo1 silencing, in mPCa cells affected the tumor microenvironment, in terms of T-cell response, evaluated either through apoptosis and cell number or cytokine release." (PMID 34199263, 2021). "Activity of Glo1 inhibitor prodrugs may deserve investigation against these tumor types." (PMID 34790575, 2021). "In established tumours increased Glo1 expression is a mediator of multidrug resistance (MDR), indicating that MG-mediated cytotoxicity may contribute to the mechanism of action of antitumour agents – possibly by induction of apoptosis and anoikis (cell detachment stimulated apoptosis)." (PMID 29100361, 2017). "Increased Glo-1 expression in tumours may be mediated through GLO-1 amplification, and also by mutation and increased transcriptional activity of Nrf2 through ARE-linked up-regulation of Glo-1 transcription." (PMID 27406712, 2016).
tumor (continued). "Overall, we have shown that GLO1-knockdown modulates the activity of glycolytic enzymes such as PK and tumor-associated properties of cells such as migration and proliferation, while overexpression of GLO1 did not affect these parameters, but rather resulted in a better adaption of cells to hypoxia." (PMID 27999356, 2016). "Consequently, elevated levels of GLO1 were found in many human tumor tissues such as colon, breast, prostate, and melanoma and in corresponding tumor cell lines, which may reflect a cellular response to increased intracellular MGO stress." (PMID 27999356, 2016). "Of note, primary PCa tumours showed high JAG1, GP2, GLO1, NPR3, VGLL3, CHRNA2 and SEMA3F mRNA levels in primary PCa tissue samples." (PMID 40219635, 2025). "Not only did silencing Glo1 lead to increased levels of methylglyoxal (MGO), but it also greatly raised the burden of lung tumors and encouraged tumor development and metastasis in vivo." (PMID 38785990, 2024). "Accordingly, Glo1 inhibitors can induce the activation of p38 and JNK stress-activated kinases; which activates downstream caspases in Glo1-overexpressing tumor cells to induce apoptosis." (PMID 35898868, 2022). "The same pathways have been described in the apoptosis induced in tumor cells by high MGO levels, which are likely at least part of the effect obtained by Glo1 interfering." (PMID 33869040, 2021). "Taken together, our data argues that Glo1 promotes methylglyoxal detoxification and NSCLC tumor growth." (PMID 31811141, 2019). "Our study represents the first demonstration that MG, via AGEs, acts as a tumor-promoting factor in ATC and suggests that MG scavengers and/or Glo1 activators merit investigations as potential therapeutic strategies for this malignancy." (PMID 31174324, 2019). "GLO1 activity and expression measured on protein CRC tumor extracts are lower in high stage tumors compared with low stage ones." (PMID 28117708, 2017). "GLO1 copy-number was increased in a large percentage of patients with GEP-NET and correlated positively with increased Glo1 protein in tumour tissue." (PMID 29100361, 2017). "Next, we implanted stably GLO1 depleted HCT116 cells on the chick embryo chorioallantoic membrane (CAM) and evaluated tumor development seven days post-implantation." (PMID 28117708, 2017). "Moreover, a high and nuclear GLO1 staining was significantly associated with a larger tumor size, but not with any other patient characteristic tested (e.g. gender, age, TNM status, pathological grading, clinical staging, alcohol and tobacco consumption or HPV status)." (PMID 28549423, 2017). "The role of Glo-1 in MDR was revealed in a transcriptome-wide subtraction technique of drug-sensitive and drug-resistant tumour cell lines." (PMID 27406712, 2016). "In GLO1-silenced experimental tumors, we further demonstrated a specific increase of YAP in the nucleus of tumor cells using immunohistochemistry." (PMID 27759563, 2016). "The glycolytic activity of tumor cells has been connected to changes in mRNA expression of enzymes related to glycolysis such as lactate dehydrogenase (LDH) and glyoxalase 1 (Glo1)." (PMID 24958267, 2013). "Although the frequency of autoantigens directed against Glo1 was low (two CRC sera, 9.5%), only, an analysis of its differential release from tumor versus normal cells presumably via exosomes should be addressed." (PMID 20184735, 2010). "If curcumin-induced Glo1 inhibition leads to accumulation of MGO, both of curcumin and MGO are expected to have similar effects at metabolic activity of tumor cells." (PMID 18946510, 2008). "In our patient cohort higher GAPDH abundance was correlated with lower MG-H1 modification frequency, less sLG accumulation in tumor as well as lower GLO1 but not GLO2 levels." (PMID 40461450, 2025). "Interestingly, contrary to Cys139 of GLO1, Cys201 of GLO2 was significantly less oxidized in tumor tissue." (PMID 40461450, 2025).
tumor (continued). "Mechanistically, GLO1 could interact with GSS and inhibit its proteasomal degradation, thereby maintaining GSH homeostasis as well as ROS levels, and preventing tumor cells elimination." (PMID 40492378, 2025). "Quantitative assays measuring MGO and MDA concentrations in tumor tissues showed a negative correlation with GLO1 expression." (PMID 40908564, 2025). "Consistent with cultured cells, was the marked increase of DNMT3B expression—but not DNMT1 and DNMT3A—in GLO1-depleted MDA-MB-231 tumor xenografts when compared with control tumors." (PMID 36998085, 2023). "Of interest in that regard, in the non-malignant state of liver cancer, GLO1 is a tumor suppressor gene." (PMID 36612084, 2022). "An increased formation of MGO in tumor cells that is not followed by a parallel increase in Glo1 activity or other detoxifying mechanisms results in toxicity." (PMID 33869040, 2021). "As opposed to our report, there is a report where GLO1 overexpression was related to high tumor grade." (PMID 35223406, 2021). "Immunohistochemical analysis indicated that GLO1 is upregulated during tumor progression, observable in HGPIN and PCa as compared to normal prostatic tissue." (PMID 34298821, 2021). "Thus, amplification of Glo1 activity detoxifies intracellular MGO and GO, which consequently promotes tumor cell survival, proliferation, angiogenesis, and invasion." (PMID 33396745, 2020). "In the non-malignant state, Glo1 acts as tumor suppressor, whereas in the highly metastatic stage with increased glycolytic flux, it promotes tumor growth and proliferation." (PMID 33396745, 2020). "In addition, the abnormal expression of Glo1 MGO metabolism is accelerated, which in turn inhibits tumor cell apoptosis." (PMID 33396745, 2020). "Moreover, GLO1 activity and argpyrimidine staining evaluated on the same CRC tumor samples were inversely correlated." (PMID 28117708, 2017). "In conclusion, we demonstrate that GLO1-knockdown in MCF-7 cells resulted in a reduction of cell proliferation and migration, while overexpression of GLO1 in HEK 293 cells revealed a better adaption to hypoxic growth conditions, which are crucial during tumor formation." (PMID 27999356, 2016). "GLO-1 amplification in tumours is not a reliable marker of this as it is not always functional and does not report on flux of MG." (PMID 27406712, 2016). "Triple negative tumors have been shown to have high levels of GLO1 indicative of this tumor's requirement for antioxidant protection." (PMID 26556877, 2016). "It is therefore not surprising that glyoxalase I inhibitors are being evaluated for use in cancer chemotherapy as they render multidrug-resistant tumours vulnerable to apoptosis." (PMID 22778743, 2012). "Moreover, we observed an inverse relationship between PJA1 expression and GLO1 levels with patient survival, further supporting the hypothesis that PJA1‐dependent GLO1 degradation contributes to tumor suppression." (PMID 40908564, 2025). "Moreover, interventions targeting the Glo1/MG-H1 axis and OPN might need to be tailored to the specific characteristics of each tumor subtype." (PMID 40362346, 2025). "In addition to TCGA, we examined GLO expression in other published NSCLC proteomic studies and observed similar effects as in our study: compared to healthy tissue, both GLO1 and GLO2 were prominently downregulated, while hypoxic targets were all upregulated in tumor." (PMID 40461450, 2025). "Therefore, inhibiting GLO1 abrogated tumor growth in vivo without any discernible off-target effects on surrounding brain cells." (PMID 29385725, 2018). "The current study suggests that overexpression of Glo1 through increased GLO1 gene copy number in patients with GEP-NET may facilitate rapid progression and resistance to therapy – assuming a role as it does in other tumour types of mediator of MDR." (PMID 29100361, 2017). "Tumour GLO1 copy number was increased, with respect to non-tumour tissue, in 19 of these cases." (PMID 29100361, 2017).
tumor (continued). "Data on AP and GLO1 immunoreactivity were available for tumor specimens of 134 patients, and revealed no AP staining in 3.7% (n = 5), low staining pattern in 20.9% (n = 28), moderate staining pattern in 31.4% (n = 42), and a high staining pattern in 44% (n = 59)." (PMID 28549423, 2017). "Other physiological parameters coinciding with glycolytic activity were high glyoxalase 1 (Glo1) and lactate dehydrogenase (LDH) enzyme activity as well as cell migration as an additional important characteristic contributing to the aggressiveness of tumor cells." (PMID 24958267, 2013). "The mean GLO1 expression in tumor tissues was 2.87-fold that in noncancerous tissues." (PMID 22479608, 2012). "Interestingly, xenograft tumor growth is inhibited when Glo1 is silenced in HCC cells carrying genetic amplification but not in cells with normal copies, supporting the potential use of Glo1 as target in tailored therapies in patients with genetic Glo1 amplification." (PMID 33869040, 2021). "There was a noteworthy distinction among FA and tumor grade (P = 0.04, Kruskal-Wallis Test) however no huge contrasts in FAN3K and GLO1 levels as indicated by clinical-histopathologic highlights of patients." (PMID 35223406, 2021). "Remarkably, our discoveries show that FA fundamentally diminishes with cutting edge tumor grade while No noteworthy contrast was seen somewhere in the range of FAN3K and GLO1 with tumor grade." (PMID 35223406, 2021). "Furthermore, we performed immunohistochemical analysis of MG stress (GLO1 and MGHs MG adducts) and HSR (HSP27) markers on our cohort of pancreatic cancer tumors treated with (n = 6) or without gemcitabine (n = 6) prior to tumor resection." (PMID 37408249, 2023). "Additionally, knockdown of Glo1, but not GPO1, significantly reduced tumor growth." (PMID 40822358, 2025).